RPS15 (ribosomal protein S15)
Diseases named in the same sentence as RPS15 in open-access papers:
RPS15 is named in the same sentence as 47 diseases in open-access papers, as found by Europe PMC text mining. Sharing a sentence is not in itself a finding about the gene and the disease. The quoted sentences say what the papers report.
chronic lymphocytic leukaemia (6 papers, 2016 to 2023). "Regarding the proteins constituting the small ribosome subunit, whole exome sequencing of chronic lymphocytic leukemia showed recurrent mutations of RPS15 while mutations of RPS20 are associated with colorectal carcinoma." (PMID 29855342, 2018). "As mutations in the C-terminal tail of human RPS15 have been observed in connection with chronic lymphocytic leukaemia, it is possible that apart from defects in translation, an impaired late pre-40S maturation step in the cytoplasm could also be a reason for this disease." (PMID 35438042, 2022). "Notably, mutations in the Rps15 C-terminal tail have been found with a high frequency in patients with relapsing chronic lymphocytic leukaemia (CLL), further substantiating the important function of the Rps15 C-terminus." (PMID 35438042, 2022). "Due to the decreasing trend of RPS15 during germ cell development, the RPS15 gene has mostly been found to be activated in tumours, such as leukaemia, chronic lymphocytic leukaemia and prostate cancer, but no studies have been seen to correlate it with sperm development." (PMID 35622500, 2022).
Diamond-Blackfan anemia (5 papers, 2012 to 2023). A congenital aregenerative and often macrocytic anemia with erythroblastopenia. "DAZAP1 and MBD3 do not currently show any evidence for their involvement in CHD; however, a missense mutation in RPS15 has been described as a possible causal candidate in a patient with complex CHD as part of Diamond Blackfan anemia." (PMID 37887000, 2023). "A case of Diamond-Blackfan anemia, a heritable human disorder characterized by a predisposition to cancer, was identified where RPS15 had been mutated." (PMID 23874713, 2013). "Congenital heterozygous inactivating mutations and deletions affecting RPL5, RPL11 and RPS15 have also been described in Diamond Blackfan Anemia (DBA), a congenital syndrome belonging to a family of human disorders, ribosomopathies, caused by impaired ribosome biogenesis and function." (PMID 28147343, 2017). "The most well characterized is Diamond Blackfan anemia (DBA), which results from haploinsufficiencies in several different RP genes (RPS24/eS24, RPS17/eS17, RPL35A/eL33, RPL5/uL18, RPL11/uL5, RPS7/eS7, RPL36/eL36, RPS15/uS19, RPS27A/eS31) and RPS19/eS19, which is mutated in 25% of patients." (PMID 33565275, 2021).
colorectal cancer (3 papers, 2018 to 2024). A primary or metastatic malignant neoplasm that affects the colon or rectum. "In conclusion, RPS15 expression is an independent prognostic factor for patients with resected colorectal cancer liver metastases and represents a potential novel therapeutic target for patients with CLRM." (PMID 38838053, 2024). "Knockdown of RPS15 expression reduced the proliferative capacity of colorectal cancer cells and increased BAX‐induced apoptotic cell death." (PMID 38838053, 2024). "This study found that RPS15 expression was an independent poor prognostic factor in colorectal cancer liver metastases." (PMID 38838053, 2024). "Present in the cytoplasm, RPS15 has been found to be activated in a variety of tumors, including esophageal cancer, colorectal cancer, and insulinoma." (PMID 38838053, 2024). "The expression of RPS15 was assessed in both primary lesions and metastatic liver lesions of colorectal cancer." (PMID 38838053, 2024). "Additionally, highly metastatic colorectal cancer cell lines exhibited increased expression of RPS15." (PMID 38838053, 2024). "In addition, mutations in the ribosomal protein genes have been found to be involved in cancers such as endometrial cancer (RPL22), chronic lymphoblastic leukemia (RPS15), colorectal cancer (RPS20), and glioma (RPL5)." (PMID 34827869, 2021). "In this study, the expression of RPS15 was upregulated in the specimens of liver metastases, and in the vivo experiment, RPS15 expression was upregulated in the highly metastatic colorectal cancer cell line compared with the primary colorectal cancer cell line." (PMID 38838053, 2024).
esophageal squamous cell carcinoma (3 papers, 2023 to 2025). Esophageal squamous cell carcinoma (ESCC) is a type of esophageal carcinoma (EC) that can affect any part of the esophagus, but is usually located in the upper or middle third. "In addition, RPS15 is involved in the development of metastasis and proliferation in human esophageal squamous cell carcinoma." (PMID 38965575, 2024). "Therefore, RPS15 inhibition combined with DDP may play a synergistic role by inhibiting the chemotherapy tolerance ability of esophageal squamous cell carcinoma." (PMID 37264021, 2023).
lung carcinoma (3 papers, 2013 to 2023). "Quantitative real-time PCR was performed to detect the fundamental expression of RPS15 mRNA in several lung cancer cell lines, including lung adenocarcinoma cell lines H1299, A549 and lung squamous cancer cell line SK-MES-1, as well as small cell lung cancer cell line H1688." (PMID 26989627, 2016). "RPL37, RPS15, and RPS20 were cloned into a mammalian expression vector and transfected into H1299 lung carcinoma cells alongside Mdm2." (PMID 23874713, 2013).
Parkinson disease (3 papers, 2018 to 2023). A progressive degenerative disorder of the central nervous system characterized by loss of dopamine producing neurons in the substantia nigra and the presence of Lewy bodies in the substantia nigra and locus coeruleus. "Likewise, in another fly model of Parkinson’s disease caused by the mutation in leucine-rich repeat kinase 2 (LRRK2), the most common genetic cause of both familial and sporadic Parkinson’s disease, global protein translation rate was elevated due to phosphorylation of ribosomal protein s15." (PMID 36711035, 2023). "A study shows that RPS15 is a critical morbific leucine-rich repeat kinase 2 (LRRK2) substrate in Parkinson’s disease models of drosophila and human neuron." (PMID 35401659, 2022).
colon cancer (2 papers, 2023 to 2024). "In this study, we observed that suppression of RPS15 expression in colon cancer cells decreased cell proliferative capacity." (PMID 38838053, 2024). "Additionally, we found that RPS15 expression was increased in colon cancer cell lines with high liver metastatic potential compared to colon cancer cell lines." (PMID 38838053, 2024). "Further analysis revealed that some of these genes, notably rps15, rpl11, rpl18, and rpl36, are significantly increased in primary adenocarcinoma tissue samples and co-ordinately predict for worse overall survival of colon cancer patients." (PMID 37888706, 2023). "Thus, RPS15 expression could be involved in suppressing apoptosis in colon cancer cells, possibly affecting cancer progression." (PMID 38838053, 2024). "Three colon cancer cell lines (DLD‐1, SW40, and HCT116) were examined for RPS15 expression by qRT‐PCR." (PMID 38838053, 2024). "On the other hand, RPL11 and RPL18 proteins had moderate intensity in colon tissue, whereas RPS15 and RPL36 showed strong staining intensity in colon cancer tissue." (PMID 37888706, 2023). "This suggests that RPS15, like RPS20, may contribute to the development of liver metastasis in colon cancer by promoting cell proliferation." (PMID 38838053, 2024). "We found that higher expression of RPS15, RPL11, RPL18 and RPL36 could individually predict worse overall survival (OS) of patients with colon cancer compared to the low expression of these genes." (PMID 37888706, 2023). "Finally, based on this evidence, we hypothesized that since these genes are implicated in similar pathways related to ribosomal biosynthesis and protein translation, RPS15, RPL11, RPL18 and RPL36 expression levels may coordinately predict the survival of patients with colon cancer." (PMID 37888706, 2023).
gastric cancer (2 papers, 2022 to 2023). A primary or metastatic malignant neoplasm involving the stomach. "This is supported by previous studies that implicate RPS15 in gastric cancer progression, proliferation and migration by affecting the Akt/IKK-β/NF-κB signaling pathway." (PMID 37888706, 2023).
Bardet-Biedl syndrome (1 paper, 2021). A ciliopathy with multisystem involvement. "For example, HES2, MAFB, RPS12, RPL12, RPS15, and AFF2 are all associated with cancer, whereas BBS12 is a gene related to Bardet-Biedl Syndrome, a multi-organ genetic disease that can involve hypoplasia of the uterus, ovaries, and fallopian tubes." (PMID 34215221, 2021).
breast carcinoma (1 paper, 2021). "The knockdown of RPS15A by shRNA in breast cancer cell line ZR-75-30 and BT474 mediates apoptosis via the activation of caspase-3 and PARP cleavage, the up-regulation of Bad and BAX and the down-regulation of Bcl-2 confirming the importance of RPS15 in the modulation of breast cancer development." (PMID 34873618, 2021).
deficiencies (1 paper, 2016). "Similarly, RP genes with myeloid-lineage specificity in our analysis, such as RPS27L, RPS15, and RPS24, have been previously implicated in bone marrow deficiencies." (PMID 27884178, 2016).
lymph node metastasis (1 paper, 2023). "Moreover, the increased RPS15 expression was significantly correlated with lymph node metastasis (Fisher exact test, P = 0.018)." (PMID 37264021, 2023). "Moreover, increased RPS15 expression was significantly correlated with lymph node metastasis." (PMID 37264021, 2023).
melanoma (1 paper, 2025). A malignant, usually aggressive tumor composed of atypical, neoplastic melanocytes. "BRAF V600K melanomas were downregulated for module 1 (RPS15, RPL29, RPL10)." (PMID 39796775, 2025).
nasopharyngeal carcinoma (1 paper, 2019). A carcinoma arising from the nasopharyngeal epithelium. "The upregulated level of RPS15 was found to be connected to nasopharyngeal carcinoma with significant roles of RPS15 in the modulation of protein translation." (PMID 30740222, 2019).
skin cancer (1 paper, 2022). "RPS15 may be associated with expression disorders in some sorts of cancer, including esophageal, lung and skin cancers." (PMID 35933451, 2022).
cancer (21 papers, 2011 to 2025). A tumor composed of atypical neoplastic, often pleomorphic cells that invade other tissues. "Despite the evidence of RPS15 being a cancer driver, the molecular mechanisms of RPS15-linked translation in promoting metastasis remain unclear." (PMID 37264021, 2023). "Moreover, Tsr1_RK is rescued by a cancer-associated mutation in the CTT of Rps15, Rps15_S136F." (PMID 37503067, 2023). "Knockdown of RPS15 increased cell apoptosis compared with scrambled siRNA‐treated control cell apoptosis in all three cancer cell lines." (PMID 38838053, 2024). "In the resected CRC and CRLM tissues, cytoplasmic RPS15 expression was observed in the cancer lesions of CRC and CRLM." (PMID 38838053, 2024). "This is because the clones of cancer cells with high RPS15 expression may survive and be enriched through the process of lesion formation." (PMID 38838053, 2024). "Additionally, CNV analysis identified amplification of PNP, FCGR3A, and CFHR1 as well as deep deletion of ETV6, CFHR1, and RPS15 as the most frequently detected copy number altered PID-related genes across the four available pediatric cancer cohorts." (PMID 36497424, 2022). "Strikingly, these included five cases (EIF1AX, HIST1H3B, MLH1, RPS15, SMARCB1) where not only the gene/protein, but also the region primarily mutated in human cancers were very ancient and could be traced back to unicellular organisms." (PMID 32731489, 2020). "In yeast, these cancer-associated mutations do not demonstrate assembly blocks or growth phenotypes, but one (Rps15_S136F, corresponding to Rps15_S139F in humans) bypasses the checkpoint for h31 folding, thereby producing ribosomes defective in start-codon selection." (PMID 36790396, 2023). "Nonetheless, given its location in the P-site, direct effects during translation arising from the Rps15 mutations cannot be ruled out and might additionally contribute to the cancer phenotype." (PMID 36790396, 2023). "Thus, the cancer-associated Rps15_S136F mutation, which leads to increased misinitiation at non-AUG codons, may perturb Rps15 directly, or affect how Ltv1 (or other, yet undescribed factors) regulates the interaction between Rps15 and the loop in Tsr1." (PMID 37503067, 2023). "However, in downregulated JTB condition, RSP5 expression was detected as downregulated and, consequently, RSP5 could emphasize an anti-tumor effect as in the case of RPS15-depleted cancer cells that suffer apoptosis under chemotherapy via upregulation of several apoptotic proteins." (PMID 36500393, 2022). "Thus, we established the stable overexpression of RPS15 in KYSE30 and KYSE450 cells and knockout of RPS15 (sgRPS15) in KYSE150 and KYSE510 cells to determine the role of RPS15 on cancer cell metastasis and growth." (PMID 37264021, 2023). "Functional and mechanistic studies of RPS15 will not only provide insight into the pathogenesis of ESCC, but also provide an opportunity to better understand how protein translation may play a key role in cancer cell metastasis." (PMID 37264021, 2023). "Our analyses did not pick up RPL22, RPS27 (eS27), RPS15 and RPL10, although already described in cancer as well." (PMID 28147343, 2017).
tumor (11 papers, 2018 to 2025). "To verify the oncogenic role of RPS15 in vivo, we established a subcutaneous transplantation tumor model in BALB/c-nude mice using RPS15 stable overexpression (RPS15) and RPS15 knockout (sgRPS15) ESCC cell lines." (PMID 37264021, 2023). "We conducted a correlation analysis between primary CRC tumor size and RPS15 expression." (PMID 38838053, 2024). "However, despite this insight into the role of RPS15 in protein translation and tumor progression, the mechanisms of translational alteration and downstream regulation remain undefined." (PMID 37264021, 2023). "To investigate whether RPS15 had an impact on tumor metastasis in vivo, we used a Red fluorescent protein (RFP)-based lung metastatic mouse model." (PMID 37264021, 2023). "For example, alterations in RPs such as RPL5 (uL5), RPL10 (uL16), RPS15 (uS19), RPL11 (uL15), and RPL22 (eL22) have been described in 10–40% of multiple tumor types." (PMID 31590378, 2019). "Furthermore, we established a subcutaneous transplantation tumor model, RFP-based lung metastatic mouse model, and popliteal lymph node metastasis model in BALB/c-nude mice using stable RPS15-overexpressing or RPS15-knockout ESCC cell lines." (PMID 37264021, 2023). "Furthermore, the results of an in vivo xenograft mouse model showed that folic acid significantly reduced tumor volume and inhibited ESCC growth, especially in the RPS15-overexpressing xenograft group." (PMID 37264021, 2023). "Moreover, alterations of RPL5, RPL10, RPS15, RPL11, and RPL22 ribosomal proteins have been described in 10 to 40% of tumor types." (PMID 33462193, 2021).
liver (1 paper, 2024). "In this study, we analyzed DEGs from a public database of primary tumor, liver metastasis, and lung metastasis gene expression data and identified RPS15 as a liver metastasis–specific prognostic factor." (PMID 38838053, 2024).
RPS15 also shares sentences with these, for which no sentence is quoted: endometrial cancer (2 papers); esophageal cancer (2); glioma (2); neurological disease (2); ovarian carcinoma (2); adenocarcinoma (1); amyotrophic lateral sclerosis (1); B-cell lymphoma (1); Diabetes (1); frontotemporal dementia (1); genetic disease (1); hepatocellular carcinoma (1); infection (1); infectious disease (1); influenza infection (1); insulinoma (1); lathosterolosis (1); leukaemia (1); lung adenocarcinoma (1); memory impairment (1); meningioma (1); monoclonal B-cell lymphocytosis (1); pancreatic cancers (1); prostate carcinoma (1); small cell lung carcinoma (1); Splenomegaly (1); squamous cell carcinoma (1); T-cell acute lymphoblastic leukemia (1); viral infections (1).